TERT (telomerase reverse transcriptase)
Diseases named in the same sentence as TERT in open-access papers (continued):
Sharing a sentence is not in itself a finding about the gene and the disease.
adenosarcoma (1 paper, 2017). A low grade malignant neoplasm characterized by the presence of a benign epithelial component (tubular and cleft-like glands) and a low grade sarcomatous component that contains varying amounts of fibrous and smooth muscle tissues. "PTs significantly more frequently displayed mutations affecting MED12, the TERT gene promoter and bona fide cancer genes, whereas adenosarcomas harbored a higher rate of MDM2/CDK4 and TERT gene amplifications." (PMID 28267263, 2017). "While TERT was preferentially altered by hotspot gene promoter mutations in PTs, only TERT gene amplification events were detected in the adenosarcomas studied here." (PMID 28267263, 2017). "Hence, in this context, despite the presence of TERT alterations in both PTs and adenosarcomas, these findings should not necessarily be interpreted as evidence of a genotypic–phenotypic correlation and of genetic similarities between these tumor types." (PMID 28267263, 2017).
adenovirus infection (1 paper, 2022). "TERT was overexpressed by lentivirus and adenovirus infection, and levels were measured using quantitative real-time polymerase chain reaction." (PMID 36299510, 2022). "In this study, we developed both in vivo and in vitro models of neonatal HIBD and overexpressed TERT using lentivirus and adenovirus infection to test this hypothesis." (PMID 36299510, 2022).
adrenocortical adenomas (1 paper, 2022). "Of note, 2 of 5 borderline adrenocortical tumors showed similar TERT gains/amplifications, while no TERT alterations were identified for 7 adrenocortical adenomas." (PMID 34549366, 2022).
airway allergy (1 paper, 2024). "The results suggest that the activities of TL/TERT/TEP1 in Tregs are associated with the pathogenesis of airway allergy." (PMID 38205251, 2024).
alpha-thalassemia mental retardation syndrome (1 paper, 2021). "These may include MGMT promoter methylation, isocitrate dehydrogenase (IDH) mutations, telomerase reverse transcriptase (TERT) mutations, 1p/19q co-deletion and alpha-thalassemia mental retardation syndrome (ATRX) mutations." (PMID 34794398, 2021).
ameloblastoma (1 paper, 2026). The most common odontogenic tumor, arising from the epithelial component of the embryonic tooth and usually affecting the molar-ramus region of the mandible or maxilla. "This study aimed to determine the frequency of TERT promoter mutations in ameloblastoma." (PMID 41975789, 2026). "TERT promoter mutations have been detected in various types of tumor; however, their prevalence in ameloblastoma has not been verified." (PMID 41975789, 2026).
amyloid (1 paper, 2018). "Considering the known protective functions of TERT, we hypothesized that an increase in mTERT- levels could confer resistance to amyloid pathology." (PMID 29930750, 2018).
amyotrophic lateral sclerosis (1 paper, 2013). Amyotrophic lateral sclerosis (ALS) is a neurodegenerative disease characterized by progressive muscular paralysis reflecting degeneration of motor neurons in the primary motor cortex, corticospinal tracts, brainstem and spinal cord. "These authors found that the over-expression of TERT plays a protective role against oxidative stress in the brain and in motor neurons, delaying the onset and the progression of amyotrophic lateral sclerosis (ALS)." (PMID 23825548, 2013).
Angiomatous Meningioma (1 paper, 2014). A WHO grade I meningioma characterized by the presence of small and medium sized vessels that predominate over the meningioma cells. "The effects of elevated TERT levels on tumor progression likely also require other companion mutations or genomic alterations that are not present in angiomatous meningioma." (PMID 25347344, 2014). "Conceivably, the copy number gains on chromosome 5 in angiomatous meningioma – which do not typically demonstrate aggressive clinical behavior – do not elevate TERT mRNA and protein levels to the same level as promoter mutations do." (PMID 25347344, 2014).
astrocytomas of the brain (1 paper, 2020). "TERT promoter mutation was the most common molecular alteration found in grade IV astrocytomas of the brain (79%, 57/72), while the H3F3A p.K27M mutation was found in nearly all grade IV IMAs (92%, 11/12)." (PMID 32771057, 2020).
autism (1 paper, 2019). Persistent deficits in social interaction and communication and interaction as well as a markedly restricted repertoire of activity and interest as well as repetitive patterns of behavior. "In addition, telomerase reverse transcriptase-overexpressing (TERT transgenic, TERT-tg) mice exhibit male-specific autism-like behaviors, as well as increases in the expression of the NMDA receptor NR2A and NR2B subunits and AMPA receptor GluR1 and GluR2 subunits." (PMID 31137494, 2019).
autism spectrum disorder (1 paper, 2022). A spectrum of developmental disorders that includes autism, and Asperger syndrome. "It is worth noting that overexpression of TERT in experimental models induces repetitive behaviors and other autism spectrum disorder (ASD)-like behavioral symptoms as well as synaptic deficits." (PMID 35159976, 2022).
Azoospermia (1 paper, 2017). Absence of any measurable level of sperm,whereby spermatozoa cannot be observed even after centrifugation of the semen pellet. "Furthermore, the TERT mRNA expression level was shown to be effective in both classifying spermatogenesis disorders in patients, and in predicting successful sperm recovery in azoospermia patients." (PMID 29019938, 2017).
B-cell neoplasm (1 paper, 2025). A group of heterogeneous lymphoid tumors generally expressing one or more B-cell antigens or representing malignant transformations of B-lymphocytes. "Furthermore, in B-cell neoplasms, TERT upregulation has been observed as a consequence of chromosomal translocation, where the TERT gene is relocated near immunoglobulin gene loci." (PMID 40723168, 2025).
Barrett adenocarcinoma (1 paper, 2013). An adenocarcinoma arising from Barrett metaplastic epithelium in the esophagus. "We went further, and similarly to the study on Barrett’s adenocarcinoma cells we show detailed consequences of TERT downregulation." (PMID 23677713, 2013).
biliary tract cancer (1 paper, 2025). "Interestingly, the variants in HFE, APOE, and TERT displayed concordant effects on HCC and biliary tract cancer." (PMID 40823170, 2025). "TERT, and telomeres, has been implicated in both HCC and biliary tract cancer in previous studies." (PMID 40823170, 2025).
bone chondrosarcoma (1 paper, 2023). A chondrosarcoma (disease) that involves the bone tissue. "The spheroid drop assay showed EEC12Z was behaving with similar invasiveness to two of the cancer cell lines (MDA-MB-231 and EM-E6/E7/TERT), and more invasively than the bone chondrosarcoma cell line SW1353." (PMID 37371583, 2023).
brain injury (1 paper, 2022). Acute and chronic (see also brain INJURIES, CHRONIC) injuries to the brain, including the cerebral hemispheres, CEREBELLUM, and brain STEM. "In a mouse model of middle cerebral artery occlusion, inhibition of TERT aggravated the injury to the microvessels and BBB, indicating that TERT is involved in the regulation of angiogenesis and BBB function after ischemic brain injury." (PMID 36299510, 2022).
brainstem tumors (1 paper, 2020). "In a more limited panel of all exons of 67 brain-tumor associated genes and the TERT promoter, alterations were detected in 82.5% of patients with brainstem tumors with an analytical sensitivity of 0.15%." (PMID 32133357, 2020).
breast fibroepithelial tumours (1 paper, 2021). "ddPCR not only succeeded in detecting TERT promoter mutations, but also revealed this mutation to be much more frequent among breast fibroepithelial tumours, especially in FA, than was previously known." (PMID 33046803, 2021).
bronchiectasis (1 paper, 2021). Segmental, irreversible dilation of the bronchial tree resulting in the accumulation of secretions which leads to obstruction. "Stratification of patients into mild-to-moderate and severe bronchiectasis revealed the differential expression in the relative telomere length, Ku70, and TERT (p < 0.05), but not SIRT1." (PMID 35071262, 2021).
bruxism (1 paper, 2022). Excessive clenching of the jaw and grinding of the teeth. "The most important result of the present study is the association of phasic bruxism episodes and TERT gene polymorphism." (PMID 35159976, 2022). "However, through regression analysis, we have shown that TERT polymorphism is a risk factor for phasic bruxism independent of the AHI value." (PMID 35159976, 2022).
cardiac hypertrophy (1 paper, 2019). "Unlike constitutive TERT overexpression by transgenesis leading to cardiac hypertrophy, AAV9-mediated TERT transfer did not produce any signs of hypertrophy at 9 to 10 weeks post treatment." (PMID 31035374, 2019).
cataract (1 paper, 2009). Partial or complete opacity of the crystalline lens of one or both eyes that decreases visual acuity and eventually results in blindness. "Preliminary phosphorylation evaluation using the Omni-Phos® Phosphorylation Assay Kit identified that ERα and TERT in both diabetic and breed-related cataract samples have more phosphorylation than normal samples." (PMID 19936027, 2009).
cerebral small vessel disease (1 paper, 2024). Cerebral small vessel disease is the term currently used to pathological processes that affect the brain parenchymal circulation (arterioles, capillaries, and veins). "However, it remains to be established as to whether TERT gene variants are associated with an elevated risk of cerebral small vessel disease (CSVD), and whether there is a causal relationship between LTL and CSVD." (PMID 39180127, 2024).
Cholestatic liver disease (1 paper, 2023). "The study also elucidates a role for epigenetic TERT repression and telomere attrition as a driver of DNA damage, cellular senescence, and fibrosis in cholestatic liver diseases, such as PSC." (PMID 37707950, 2023).
chronic heart failure (1 paper, 2018). "MiR-146a was up-regulated in senescent cells and inversely correlated with telomere length and TERT activity, when measured in angiogenic cells from chronic heart failure patients and healthy control subjects." (PMID 30208911, 2018).
chronic hepatitis B (1 paper, 2018). "In this study, we investigated the association between the polymorphisms of telomerase reverse transcriptase (TERT) gene and the risk of chronic hepatitis B (CHB) in a Chinese Han population." (PMID 29507683, 2018).
chronic lung allograft dysfunction (1 paper, 2021). Chronic lung allograft dysfunction encompasses a range of pathologies that cause a transplanted lung to not achieve or maintain normal function. "Moreover, it has been found that IPF with mutations in TERT, RTEL1, or PARN has a significantly higher risk of death and chronic lung allograft dysfunction compared to those in patients without these mutations." (PMID 34859008, 2021).
cleft lip (1 paper, 2013). Congenital defect in the upper lip where the maxillary prominence fails to merge with the merged medial nasal prominences. "The chromosome 5p15.33 locus contains two well-known genes, telomerase reverse transcriptase (TERT) and cleft lip and palate trans-membrane 1-like (CLPTM1L), which have been implicated in carcinogenesis." (PMID 24260099, 2013).
CNS lymphomas (1 paper, 2022). "Here, the authors complete whole genome sequencing and RNA-seq to characterize 51 PCNSLs, and find common mutations in immune pathways and upregulated TERT expression and find distinct pathway differences between DLBCL and other primary CNS lymphomas." (PMID 35538064, 2022).
colorectal adenocarcinoma (1 paper, 2018). The most common type of colorectal carcinoma. "Currently, only onestudy evaluated TERT mutation frequency in CRC, and no mutationswere found in colorectal adenocarcinomas (Killelaet al., 2013)." (PMID 29473934, 2018). "Our results are in agreementwith a previous report that showed the absence of TERT promotermutation in colorectal adenocarcinomas (Killelaet al., 2013)." (PMID 29473934, 2018).
colorectal tumor (1 paper, 2008). "We determined the feasibility of this RMEAM strategy by assessing the methylation density of CpG islands located in the promoter regions of MLH1, TERT and MGMT, and it has been proved that the mathylation of MLH1, TERT and MGMT are associated with carcinogenesis of colorectal tumor." (PMID 18237388, 2008).
conjunctiva (1 paper, 2018). "In our cohort the frequency of UV-related TERT promoter mutations was significantly higher in HIV-positive compared to HIV-negative conjunctiva neoplasia cases suggesting a synergistic effect of the virus with UV in the accumulation of DNA damages." (PMID 29562930, 2018). "Overall, TERT promoter mutations were detected in 23 out of 72 (31.9%) conjunctiva neoplasia cases, in one out of 53 (1.9%) control tissues and were absent in KS lesions." (PMID 29562930, 2018). "The average prevalence of TERT promoter mutations in conjunctiva neoplasia was 31.9%." (PMID 29562930, 2018). "In this study we have assessed the presence of TERT promoter mutations in HIV-positive and HIV-negative conjunctiva neoplasia cases to identify a possible synergistic effect of HIV on the accumulation of UV-induced mutations." (PMID 29562930, 2018). "Moreover, the occurrence of TERT promoter mutation in conjunctiva neoplasia was not affected by the HPV or HHV8 infection status." (PMID 29562930, 2018).
cyst (1 paper, 2013). A sac-like closed membranous structure that may be empty or contain fluid or amorphous material. "In the TERT siRNA group, the spinal cord also appeared to have visible structural damage, inflammatory cell infiltration, neuronal loss and disintegration, glial cell hypertrophy and hyperplasia, cyst formation and other phenomena, all of which were milder than those in the SCI only group." (PMID 23793903, 2013).
dependence (1 paper, 2014). "Among our four ‘control’ genes, gene variations in TERT (rs2736100 and rs2853676) and CLPTM1L (rs401681 and rs31489) have a significant direct association with lung ADC risk but not an indirect effect through nicotine dependence." (PMID 25233467, 2014).
diaphragmatic disease (1 paper, 2022).
dilated cardiomyopathy (1 paper, 2012). Cardiomyopathy which is characterized by dilation and contractile dysfunction of the left and right ventricles.
embryonal tumors (1 paper, 2013). "Studies have shown that large increases in chromosomal material in the 5p15 region, where the TERT gene is located, are detectable in MB, suggesting that the TERT gene could be amplified in CNS embryonal tumors." (PMID 24152672, 2013).
endocrine cancers (1 paper, 2014). "As the majority of endocrine cancers exhibit high TERT levels, additional, unknown genetic or epigenetic, events may explain the observed association between TERT gene upregulation and malignant phenotype." (PMID 24803525, 2014). "The finding of specific TERT promoter mutations in subsets of endocrine cancers could suggest that these tumors share a common molecular denominator regarding the acquisition of cellular immortality." (PMID 24803525, 2014). "Moreover, our findings might explain why the subsets of endocrine tumors regularly exhibit high levels of TERT gene expression." (PMID 24803525, 2014).
endometrial tumour (1 paper, 2015). "Our analysis of microarray datasets suggested differences in CLPTM1L expression between endometrial tumour histological subtypes, and increased expression of both TERT and CLPTM1L between endometrial tumour and normal tissue." (PMID 25487306, 2015).
erectile dysfunction (1 paper, 2022). Persistent or recurrent inability to achieve or to maintain an erection during sexual activity. "Telomerase reverse transcriptase-circulating endothelial progenitor cells from fetal brain vasculature could repair erectile dysfunction of rats with cavernous nerve injury." (PMID 36451096, 2022).
essential thrombocythemia (1 paper, 2017). A chronic myeloproliferative neoplasm that involves primarily the megakaryocytic lineage. "When stratified by disease subtypes, the JAK2 46/1 haplotype and JAK2 rs12339666 were significantly associated with all three MPN subtypes, but TERT rs2736100 was only associated with essential thrombocythemia and polycythemia vera." (PMID 29100304, 2017).
follicular lymphoma (1 paper, 2012). Follicular lymphoma is a form of non-Hodgkin lymphoma characterized by a proliferation of B cells whose nodular structure of follicular architecture is preserved. "For example, ID4 has been shown to act as a putative tumour suppressor gene in AML, DCC is hypermethylated in follicular lymphoma and mutation of TERT increases the risk of familial AML." (PMID 22479372, 2012).
glomerulopathies (1 paper, 2012). "More importantly, TERT upregulation and β-catenin stabilization were also found in human and mouse HIV-associated glomerulopathies, indicating that TERT-mediated Wnt activation can be required for podocyte proliferation in these diseases." (PMID 23061047, 2012). "The observation that TERT silencing and Wnt pathway inactivation in transgenic mice can revert the podocyte phenotype suggests TERT and Wnt as new targets to fight collapsing glomerulopathies." (PMID 23061047, 2012).
hemangiopericytoma (1 paper, 2014). An antiquated term that refers to benign or malignant mesenchymal neoplasms characterized by the presence of neoplastic spindle-shaped to round cells arranged around thin-walled branching vascular spaces. "However, TERT promoter mutation might be dependent on the anatomic site of presentation, since cranial SFTs and hemangiopericytomas, which are now considered to belong to the SFT family from a genetic perspective, have a slightly higher mutation frequency (11/43; 26%)." (PMID 24726063, 2014).
HIV-1 infection (1 paper, 2023). The type species of lentivirus and the etiologic agent of acquired immunodeficiency syndrome (AIDS). "To study the potential role of LysRS in regulating USF2 in HIV-1 infected cells, we examined the mRNA transcript levels of TERT, PTPN6 and TGFb1 when the function of pS207-LysRS was blocked during HIV-1 infection." (PMID 37933844, 2023).
Hutchinson-Gilford progeria (1 paper, 2022). "In mouse models of Hutchinson-Gilford progeria, TERT gene therapy was shown to reverse vascular senescence and extend the lifespan." (PMID 36552277, 2022).
Hürthle cell adenomas (1 paper, 2020). "Mutation panel false positive results occurred in a 33% (11/33) of Hürthle cell adenomas, with the majority (9/11) due to individual RAS mutations and one due to an individual TERT promoter mutation." (PMID 32767735, 2020). "One of only four positive MPTX results in Hürthle cell adenomas was due to an individual TERT promoter mutation that did not coexist with other mutations." (PMID 32767735, 2020).